CLPP (caseinolytic mitochondrial matrix peptidase proteolytic subunit)
Description:
Protease component of the ClpXP complex that cleaves peptides and various proteins in an ATP-dependent process. Has low peptidase activity in the absence of CLPX. The ClpXP complex can degrade CSN1S1, CSN2 and CSN3, as well as synthetic peptides (in vitro) and may be responsible for a fairly general and central housekeeping function rather than for the degradation of specific substrates. Cleaves PINK1 in the mitochondrion.
Synonyms: DFNB81; PRLTS3
Tractability: Small molecule: a structure with a bound ligand is known. PROTAC: ubiquitination databases record sites on it; its protein half-life has been measured; a small molecule that binds it is known.
Target class: Enzyme; Hydrolase
Gene: Protein-coding gene on chromosome 19 (6,361,427 to 6,370,242, forward strand). Ensembl gene ENSG00000125656.
Subcellular location: Mitochondrion matrix
Subcellular location (Human Protein Atlas): Mitochondria
Pathways (Reactome):
Metabolism of proteins: Mitochondrial protein degradation
Gene Ontology:
Molecular function: endopeptidase activity; protein binding; serine-type endopeptidase activity; ATP-dependent peptidase activity; ATPase binding; peptidase activity; identical protein binding
Biological process: membrane protein proteolysis; protein catabolic process; proteolysis; mitochondrial protein catabolic process; protein quality control for misfolded or incompletely synthesized proteins
Cellular component: endopeptidase Clp complex; mitochondrial matrix; mitochondrion
Genetic constraint (gnomAD): Loss-of-function variants: 12 observed, 20.77 expected, observed/expected ratio (o/e) 0.58, 90% interval 0.37 to 0.94. The synonymous counts are far from expectation, so gnomAD's model fits this gene poorly and the ratio says little. Missense variants: 354 observed, 360.67 expected, observed/expected ratio (o/e) 0.98, 90% interval 0.9 to 1.07. Synonymous variants: 192 observed, 145.1 expected, observed/expected ratio (o/e) 1.32, 90% interval 1.18 to 1.49.
Gene-disease validity (ClinGen):
ClinGen rates the evidence that CLPP causes each of these diseases.
Perrault syndrome 3 (autosomal recessive): Definitive.
Homologues: Orthologues: chimpanzee CLPP (99% identical), macaque CLPP (97% identical), dog CLPP (90% identical), pig CLPP (89% identical), guinea pig CLPP (86% identical), mouse Clpp (86% identical), rat Clpp (83% identical), tropical clawed frog clpp (71% identical), zebrafish clpp (69% identical), rabbit CLPP (61% identical), Drosophila melanogaster ClpP (54% identical), Caenorhabditis elegans clpp-1 (46% identical).
Diseases named in the same sentence as CLPP in open-access papers:
CLPP is named in the same sentence as 114 diseases in open-access papers, as found by Europe PMC text mining. Sharing a sentence is not in itself a finding about the gene and the disease. The quoted sentences say what the papers report.
Perrault syndrome (35 papers, 2015 to 2025). Perrault syndrome (PS) is characterized by the association of ovarian dysgenesis in females with sensorineural hearing impairment. "The importance of ClpP in CNS health is further emphasized by Perrault syndrome (PRLTS), caused by biallelic CLPP loss-of-function mutations, leading to hearing loss, ovarian insufficiency, and CNS white matter abnormalities." (PMID 41155556, 2025). "A CLPP variant has been associated with human Perrault Syndrome, which includes phenotypic features of truncal and cerebellar ataxia." (PMID 41300811, 2025). "Currently, it is reported that human CLPP gene mutation has a clinical phenotype of Perrault syndrome or POI." (PMID 38694941, 2024). "In contrast to other forms of Perrault syndrome with exclusively female infertility due to primary ovarian insufficiency, CLPP absence according to mouse data also causes male infertility due to azoospermia after diplotene arrest." (PMID 38927630, 2024). "These variants in CLPP have been discovered to cause Perrault syndrome associated with hearing loss and ovarian dysfunction as well as neurologic features." (PMID 37148394, 2023). "To date, 13 different variants of CLPP have been associated with Perrault syndrome, which is genetically heterogeneous." (PMID 37007963, 2023). "The connection between ERAL1 and CLPP is especially intriguing, since CLPP is also associated with the Perrault syndrome." (PMID 37860580, 2023). "In Mus musculus, animals with deficiency of CLPP were characterized recently, and in Homo sapiens, the investigation of patients with Perrault syndrome revealed underlying CLPP mutations." (PMID 35954215, 2022). "In contrast, variants in CLPP linked to Perrault syndrome are clustered mainly in a single 20 residue region of the CLPP protein." (PMID 31827252, 2020). "They suggested that this finding was consistent with ovarian failure associated with CLPP missense and splice-site mutations found in a variant of human Perrault syndrome, in which streak ovaries with few scattered follicles had been described." (PMID 33374937, 2020). "Variants in CLPP induce Perrault syndrome (type 3), which presents with sensorineural hearing loss and ovarian failure." (PMID 33426505, 2020). "During the same year, by a combination of homozygosity mapping, linkage analysis and exome sequencing in three families, CLPP recessive mutations were identified in a Pakistani family with Perrault syndrome." (PMID 31067645, 2019). "ClpP deficiency causes Perrault syndrome characterized by sensorineural hearing loss and premature ovarian failure in humans." (PMID 30877431, 2019). "In contrast, clpP-recessive mutations were observed and identified as the cause of infertility and sensorineural deafness of Perrault syndrome." (PMID 31067645, 2019). "Recently, several mutations in the mitochondrial protease CLPP have been identified in patients with Perrault syndrome 3 (PRLTS3)." (PMID 30150665, 2018). "We found that in this case MRI data are predictive for the severity of the clinical manifestations and can be used to identify severe cases of Perrault syndrome due to CLPP mutations." (PMID 27899912, 2016). "In human Perrault syndrome (PS), characterized by sensorineural hearing loss and ovarian failure, ClpP mutations are assumed as causative for the disease." (PMID 26679294, 2015). "Given that mutations in the mitochondrial leucine tRNA-ligase LARS2 cause the Perrault syndrome just like CLPP deficiency, this observation may further strengthen the notion that RNA processing is important in this pathogenesis." (PMID 38139332, 2023). "The deficit in the reduction of mtDNA and mitochondrial numbers may underlie infertility in the CLPP variant of the recessive Perrault syndrome." (PMID 37007963, 2023). "Similarly, recessive CLPP mutations in the human CLPP genes are linked to a rare genetic disease Perrault syndrome, which shows infertility and hearing loss." (PMID 37046596, 2023).
Perrault syndrome (continued). "While the precise role of CLPP in mtDNA maintenance is not known, mtDNA-release-mediated cGAS–STING signaling may be involved in Perrault syndrome caused by CLPP mutations." (PMID 37001140, 2023). "Mutations in CLPP cause Perrault syndrome, with phenotypes similar to defects in mtDNA/mtRNA." (PMID 35954215, 2022). "Our prior work had documented that deficiency of ClpP in mouse cells leads to mtDNA instability and nucleoid enlargement, but whether these features could be recapitulated in Perrault syndrome patients is unknown." (PMID 34943861, 2021). "These anomalies may be ClpP-specific, but perhaps similar data might also be found in other variants of Perrault syndrome." (PMID 34345994, 2021). "The consistent dysregulation of these factors from an early age might influence also human Perrault syndrome, where ClpP loss-of-function leads to early infertility and deafness, with subsequent widespread neurodegeneration." (PMID 34345994, 2021). "As such, analysis of the different pathogenic mutations in CLPP might provide evidence for a link to the severity of the disease observed in different Perrault syndrome patients." (PMID 30150665, 2018). "Mitochondrial dysfunction is present in some genetic diseases, such as Perrault syndrome, individuals with POLG mutations, and individuals with CLPP mutations, all exhibiting clinical phenotypes of ovarian dysfunction and infertility." (PMID 38694941, 2024). "We have recently shown that the whole-body CLPP knockout mice (Clpp−/−) are sterile with shorter stature, as observed in Perrault syndrome patients." (PMID 32467259, 2020). "Biallelic variants in CLPP and LARS2 are known to cause Perrault syndrome, a rare autosomal recessive disorder characterized by sensorineural HL in both sexes and primary ovarian failure in females." (PMID 32842620, 2020). "To date, biallelic variants in six causative genes have been associated with Perrault syndrome:HSD17B4 (MIM 233400), HARS2 (MIM 614926), LARS2 (MIM 615300), CLPP (MIM 614129), C10orf2 (MIM 616138), and ERAL1 (MIM 607435)." (PMID 31827252, 2020). "ClpP knockout mice exhibit growth retardation, mtDNA accumulation, inflammatory response and infertility, recapitulating the pathology of Perrault syndrome in humans." (PMID 30877431, 2019). "Human ClpP connection with cancer and Perrault syndrome will be the focus of many studies in the coming years." (PMID 31067645, 2019). "Ouridentification of ERAL1 as a Perrault syndrome gene further ties CLPP and ERAL1 together, asmutations in either of them lead to similar pathology in humans." (PMID 28449065, 2017). "This consistency contrasts with other genes associated with Perrault syndrome where brain white matter changes are variable in frequency, from commonly present in individuals with CLPP-associated Perrault syndrome to absent with HARS2-associated disease." (PMID 40043708, 2025). "Pathogenic/likely pathogenic variants in HARS2, CLPP, LARS2, TWNK, ERAL1, and PROPR may cause Perrault syndrome-related OD." (PMID 38812815, 2024). "In contrast, the early-onset infertility typical of ClpP-mutant Perrault syndrome could be due to meiosis defects, where the handling of nuclear DNA is impaired in similar ways as the handling of mitochondrial nucleoids in ClpP cells." (PMID 34345994, 2021). "Clearly, the role of ClpP for Perrault syndrome might become more understandable if its dysfunction controls the abundance/multimerization/target interaction/activity of the PRLTS disease protein Twinkle at the nucleoid." (PMID 34943861, 2021). "In the human mitochondria, ClpP regulates the homeostasis of proteins involved in the cellular metabolic pathways such as the electron transport chain, and the expression of ClpP is related to carcinomas, infertility, and sensorineural deafness of Perrault syndrome." (PMID 33613462, 2020).
Perrault syndrome (continued). "Consistent with an important role for CLPP in Perrault syndrome, CLPP null mice (CLPP−/−) also display infertility, deafness and growth retardation." (PMID 30150665, 2018). "It is noteworthy that none of the Perrault syndrome disease proteins were dysregulated, except HSD17B4 that showed a significant upregulation only in patient fibroblasts, meaning the role of ClpP cannot be explained by abnormal degradation of a Perrault syndrome disease protein, by this dataset." (PMID 34943861, 2021).
acute myeloid leukemia (20 papers, 2015 to 2025). Acute myeloid leukemia (AML) is a group of neoplasms arising from precursor cells committed to the myeloid cell-line differentiation. "ALAS1, the rate limiting step of heme biosynthesis, has previously been identified as a ClpP substrate and loss of heme biosynthesis has been implicated as a metabolic vulnerability in acute myeloid leukemia." (PMID 37063293, 2023). "ClpP is upregulated in acute myeloid leukemia (AML) specimens and loss of ClpP decreases viability of AML cells." (PMID 35653190, 2022). "A number of tumor-related reports reveal that ClpP is involved in cancer promotion in various cancers like acute myeloid leukemia, breast cancer, pancreatic cancer, and colon cancer." (PMID 40395852, 2025). "Modifiers of ClpP activity have previously shown anticancer properties, with both inhibitors and activators of ClpP demonstrating antitumor efficacy for acute myelogenous leukemia." (PMID 35929764, 2022). "In that study, the ClpXP subunit ClpP was found overexpressed in a subset of human acute myeloid leukemias, and pharmacologic or genetic targeting of ClpP impaired mitochondrial oxidative phosphorylation, resulting in leukemia cell killing." (PMID 27389535, 2016). "While most studies have focused on hematological malignancies, particularly acute myeloid leukemia, where ClpP activation leads to mitochondrial dysfunction and selective cancer cell death, its role in solid tumors—especially brain tumors-remains comparatively underexplored." (PMID 41155556, 2025). "The ClpP is overexpressed in approximately 40% of Acute Myeloid Leukemia (AML) patients." (PMID 36389399, 2022). "In acute myeloid leukemia (AML), ClpP activators can destroy leukemic stem cells and help defeat resistance to BCL-2 inhibitors." (PMID 41155556, 2025). "The mitochondrial proteases neurolysin (NLN) and caseinolytic protease P (CLPP) have been identified as therapeutic targets in acute myeloid leukemia (AML)." (PMID 32761807, 2020). "In addition, recent data also suggest that targeting mitochondrial ClpP could be an effective anticancer strategy for malignancies such as acute myeloid leukemia." (PMID 33037181, 2020). "Hyper-activation of ClpP by ONC201 increases mitochondrial proteolysis and leads to mitochondrial dysfunction, impaired oxidative phosphorylation, and death of acute myeloid leukemia cells." (PMID 34642468, 2022). "Similarly, in acute myeloid leukemia (AML), upregulation of ClpP expression is observed." (PMID 40395852, 2025). "Human acute myeloid leukemia (AML) cell lines lacking ClpP undergo cell death following abnormal protein accumulation and mitochondrial respiration impairment." (PMID 35269393, 2022). "The expression level of ClpP is greater in acute myeloid leukemia (AML) cells than in normal hematopoietic cells." (PMID 32195060, 2020). "For example, CLPP is often overexpressed in acute myeloid leukemia (AML) and its inhibition induces death in AML cells, but not in normal hematopoietic cells." (PMID 32094149, 2020). "Recently, the mitochondrial proteases caseinolytic protease P (CLPP) and neurolysin (NLN) have been identified as therapeutic targets in acute myeloid leukemia (AML)." (PMID 32761807, 2020).
Infertility (20 papers, 2018 to 2024). "Despite protective efforts in eukaryotes, eventually, the toxic accumulation of mtDNA and mtRNA will cause infertility, deafness, and broader neurodegeneration, as well as innate immunity activation during the ageing process in CLPP-mutant eukaryotes." (PMID 35954215, 2022). "ClpP deficiency in mouse also causes reduced body size with leanness, even before the manifestation of complete infertility and hearing impairment." (PMID 34943861, 2021). "Recessive CLPP mutations have been found to cause the human Perrault variant of ovarian failure and sensorineural hearing loss, and global germline Clpp knockout female mice showed auditory deficits and complete infertility." (PMID 37007963, 2023). "Thus, mutations in the CLPP interactome lead to the combination of infertility with deafness, which is the hallmark of autosomal recessive PRLTS." (PMID 35954215, 2022). "The complete diplotene arrest observed in CLPP-null mice is thus unique in its phenotype compared to other mitochondrial deficiencies, and also rather exceptional in comparison to arrest phenotypes in other mouse infertility models." (PMID 36611846, 2022). "Thus, the phenotype produced by CLPP mutations with a combination of infertility and of sensorineural hearing impairment is highly specific." (PMID 35954215, 2022). "Moreover, it will be important to monitor patients treated with CLPP inhibitors for hearing loss or infertility." (PMID 32761807, 2020). "The loss of caseinolytic peptidase P (CLPP) leads to infertility in mice." (PMID 32614449, 2020). "In animal experiments, CLPP-/- mice showed auditory defects and complete infertility, and the ovarian reserve in mice showed an accelerated state of depletion with age." (PMID 38694941, 2024). "Mammalian CLPP deletion triggers infertility, deafness, growth retardation, and cGAS-STING-activated cytosolic innate immunity." (PMID 38927630, 2024). "Prominently strong reductions were found in testis, as the most severely affected tissue of CLPP-null mice that model the complete infertility of PRLTS3 patients." (PMID 38139332, 2023). "This concept is in good agreement with the main CLPP-null phenotypes, namely deafness that is frequently triggered by improper mtRNA processing and infertility with meiotic arrest, which was repeatedly described as a consequence of altered mtDNA processing." (PMID 35954215, 2022). "This insight is relevant to improve ClpP-modulating drugs that block bacterial growth and for the treatment of human infertility, deafness, and neurodegeneration." (PMID 35954215, 2022). "Previously, it was described that CLPP-null male mice displayed a complete absence of mature spermatids and spermatozoa, explaining the early complete infertility of this mutant mouse that models PRLTS3." (PMID 36611846, 2022). "Mutations in ClpP in humans lead to the development of Perrault syndrome 3 (PRLTS3), which is modeled by ClpP−/− mice that mirror the infertility, sensorineural hearing loss, ataxia and growth retardation known from PRLTS3 patients." (PMID 31547314, 2019). "In CLPP-null mice used as a PRLTS3 model, both females and males are completely infertile, with a growth deficit despite increased food consumption, reduction of body length by 10% and weight by 30%, as well as a reduction of fat mass by 64% and lean mass by 24%." (PMID 38397478, 2024). "The present case reported a new CLPP variant with clinical manifestations of reduced ovarian function and infertility without hearing impairment or other clinical manifestations." (PMID 37007963, 2023). "Importantly, PRLTS3 patients share a number of phenotypes (such as deafness and infertility in both sexes) with CLPP null mice (CLPP−/−) which provides strong support for a link between the mutations in CLPP and PRLTS3." (PMID 30150665, 2018).
Infertility (continued). "Likewise, human patients harboring mutations in ClpP acquired only hearing loss and infertility, thus suggesting that the loss of ClpP is not incompatible with life but seems to affect mostly cells relying on oxidative phosphorylation." (PMID 34207660, 2021). "However, ClpP−/− mice are viable and showed only infertility and a slight decrease in size." (PMID 34207660, 2021). "Similarly, CLPP−/− mice have impaired hearing and are infertile." (PMID 32761807, 2020). "Many meiotic processes show sexual dimorphism in their requirements, but the infertility of both sexes in the CLPP-null mouse model does not yet reveal whether this could be the case." (PMID 36611846, 2022). "Thus, a straightforward therapeutic avenue for CLPP-null infertility by anti-inflammatory intervention could not be substantiated." (PMID 36611846, 2022).